SPRY2 (sprouty RTK signaling antagonist 2)
Diseases named in the same sentence as SPRY2 in open-access papers (continued):
Sharing a sentence is not in itself a finding about the gene and the disease.
osteoarthritis (2 papers, 2022 to 2025). A noninflammatory degenerative joint disease occurring chiefly in older persons, characterized by degeneration of the articular cartilage, hypertrophy of bone at the margins and changes in the synovial membrane. "LOF + MIS variants in ADAMTS6, SPRY2 and COLGALT2 are protective against osteoarthritis, whereas aggregation of these variants in ADAMTSL3, VIT, IL11 and THBS3 confer risk of osteoarthritis." (PMID 40205036, 2025).
prostatic intraepithelial neoplasia (2 papers, 2015 to 2018). "In conclusion, loss of a single allele of either Spry1 or Spry2 results in the development of prostate intraepithelial neoplasia in mice." (PMID 26075267, 2015). "Recently, it was demonstrated that concomitant prostate-specific deletion of Spry1 and Spry2 in mice resulted in prostatic intraepithelial neoplasia (PIN), while deletion of either Spry 1 or Spry 2 in hemizygous Pten null mice resulted in invasive carcinoma." (PMID 26075267, 2015). "We have previously demonstrated that prostate‐specific heterozygous loss of Spry2 does not result in tumour formation, while the heterozygous loss of Pten alone causes PIN (prostatic intraepithelial neoplasia) lesions." (PMID 29540470, 2018).
psoriasis (2 papers, 2020 to 2021). An autoimmune condition characterized by red, well-delineated plaques with silvery scales that are usually on the extensor surfaces and scalp. "It is demonstrated that IL-22 can increase expression of miR-122-5p, inhibit expression of Spry2, promote proliferation of keratinocytes, and eventually cause occurrence of psoriasis." (PMID 33975513, 2021). "IL-22-induces miRNA-122-5p which promotes keratinocyte proliferation by decreasing the expression of Spry2 in the pathogenesis of psoriasis." (PMID 33231565, 2020).
sarcoma (2 papers, 2014 to 2019). A usually aggressive malignant neoplasm of the soft tissue or bone. "The major role of Spry2 is the inhibition of the rat sarcoma RAS/extracellular signal-regulated kinase (ERK) pathway, whereas PTEN acts mainly as an inhibitor of the phosphoinositide 3-kinase (PI3K)/Akt pathway." (PMID 32038175, 2019). "They provided evidence that Spry2 is necessary for sarcoma formation by patient-derived fibrosarcoma cell lines or HRAS oncogene-transformed human fibroblasts through EGFR signaling." (PMID 24744103, 2014).
adenoma (1 paper, 2021). A neoplasm arising from the epithelium. "Overall, our results clearly demonstrate the early onset of SPRY2 upregulation in benign adenomas (early stage), which also continued during the stage of adenocarcinoma." (PMID 34685612, 2021). "In this regard, analysis of GEO datasets showed that SPRY2 transcripts are increased in adenomas compared to normal mucosa." (PMID 34685612, 2021). "We evaluated SPRY2 mRNA expression in benign adenomas and matched control tissue in a publicly available dataset using the GEO2R software tool located in the National Center for Biotechnology Information (NCBI) database (GSE8671)." (PMID 34685612, 2021). "An overall increase in SPRY2 transcripts in adenomas compared to adjacent control mucosa from matched patient samples was noted." (PMID 34685612, 2021). "Furthermore, the changes in SPRY2 5mC and 5hmC in adenocarcinomas observed in CRC patients from this study may have clinical implications as it pertains to identifying potential adenocarcinomas that may originate from precancerous adenomas and therefore warrants further studies." (PMID 34685612, 2021).
Arrhythmia (1 paper, 2022). Any cardiac rhythm other than the normal sinus rhythm. "SPRY2 regulates a normal heart rate by modulating the activity of the calcium ion channels in the myocardium and the sinoatrial node; therefore, reduced SPRY2 is associated with arrhythmias." (PMID 35933342, 2022).
asthma (1 paper, 2021). "Spry2 deficiency abrogated type 2 inflammation and airway hyperreactivity in a murine model of asthma." (PMID 33684096, 2021). "To further evaluate its contribution to human asthma, we assayed Spry2 expression in CD4+ T cells from blood and BAL from patients with asthma and disease controls by flow cytometry." (PMID 33684096, 2021). "Spry2 expression was higher in blood and airway CD4+ T cells from patients with asthma, and Spry2 knockdown impaired human T cell proliferation and cytokine production." (PMID 33684096, 2021). "Our results demonstrated that Spry2 in CD4+ T cells is indispensable for the asthma phenotype." (PMID 33684096, 2021). "The expression level of Spry2 in CD4+ T cells from blood and BAL was significantly higher in patients with asthma." (PMID 33684096, 2021).
cataract (1 paper, 2016). Partial or complete opacity of the crystalline lens of one or both eyes that decreases visual acuity and eventually results in blindness. "The distinct expression patterns of Spry2 and α-SMA suggested that these two types of cataracts underwent different pathological changes." (PMID 27415760, 2016).
cyst (1 paper, 2014). A sac-like closed membranous structure that may be empty or contain fluid or amorphous material. "Neither control nor experimental mammary epithelia, including both Spry2Δ/Δ and Spry2-GOF epithelia, invaded toward beads pre-soaked in bovine serum albumin (BSA) or beads soaked in FGF2, which stimulate cyst formation (not shown), during the 72-hour time course." (PMID 24718286, 2014).
dementia (1 paper, 2024). Loss of intellectual abilities interfering with an individual's social and occupational functions. "Another example is SPRY2, highlighted in our study as a suggestive gene for VaD, with strong functional associations with known AD and related dementias genes." (PMID 39046104, 2024).
endometriosis (1 paper, 2023). The growth of functional endometrial tissue in anatomic sites outside the uterine body. "According to the present findings, MeP and ƩPBs might downregulate SPRY2 expression and thereby favor invasiveness and metastasis in women with endometriosis." (PMID 38069001, 2023). "Finally, although the importance of SPRY2 in endometriosis is unknown, it plays a crucial role in the regulation of cancer cell invasion." (PMID 38069001, 2023). "The sole difference in expression between endometriosis stages was observed for two genes related to the invasion, migration, and metastasis pathway (FUT8 and SPRY2 genes), which showed higher gene expression levels in patients with stages III/IV." (PMID 38069001, 2023).
epilepsy (1 paper, 2016). A brain disorder characterized by episodes of abnormally increased neuronal discharge resulting in transient episodes of sensory or motor neurological dysfunction, or psychic dysfunction. "While astrogliosis is enhanced in Spry2/4+/− mice, neuronal cell loss and GCD are clearly reduced indicating that Spry2/4 may serve as pharmacological targets in epilepsy or in other neurodegenerative diseases." (PMID 26540287, 2016).
gastric adenocarcinoma (1 paper, 2017). "As the result, we demonstrated that FGFR2 high-expression and SPRY2 low-expression were significantly associated with unfavorable prognosis of gastric adenocarcinoma." (PMID 28002800, 2017). "In conclusion, we demonstrated that SPRY2 low-expression is a biomarker for unfavorable prognosis in gastric adenocarcinoma." (PMID 28002800, 2017). "The mRNA levels of FGFR2 and SPRY2 were detected by quantitative PCR in 11 samples of gastric adenocarcinoma, including tumor tissues, adjacent tumor tissues and invaded lymph nodes." (PMID 28002800, 2017). "As the result, we demonstrated that both FGFR2 high-expression and SPRY2 low-expression indicated poorer prognosis of gastric adenocarcinoma." (PMID 28002800, 2017). "On the contrary, SPRY2 had significantly higher mRNA level in adjacent tissues compared with tumor or lymph node, suggesting SPRY2 as a tumor suppressor in gastric adenocarcinoma." (PMID 28002800, 2017). "The expression of SPRY2 in gastric adenocarcinoma cell lines including KatoIII, SNU16, SNU1 and SGC7901 were detected by Western blotting." (PMID 28002800, 2017). "Moreover, FGFR2 high-expression (P = 0.031, 5-year survival rate: 52.2% vs. 35.9%) and SPRY2 low-expression (P = 0.020, 5-year survival rate: 43.2% vs. 61.3%) were also demonstrated to be biomarkers for poorer prognosis in gastric adenocarcinoma." (PMID 28002800, 2017). "Moreover, SPRY2 low-expression could indicate advanced T stage and positive lymphatic invasion (P = 0.002 and 0.001, respectively), suggesting the suppressive role of SPRY2 in gastric adenocarcinoma growth and invasion." (PMID 28002800, 2017).
gastric tumor (1 paper, 2017). "In our study, tumors with SPRY2 knockdown (upper row) had remarkably larger sizes than these without SPRY2 knockdown (lower row), confirming the suppressor role of SPRY2 in gastric tumor growth." (PMID 28002800, 2017).
geographic atrophy (1 paper, 2025). "Consequently, SPRY2 might also inhibit geographic atrophy, positioning it as a potential alternative therapeutic option to aflibercept." (PMID 40141227, 2025).
idiopathic pulmonary fibrosis (1 paper, 2022). Idiopathic pulmonary fibrosis (IPF) is a nonneoplastic pulmonary disease that is characterized by the formation of scar tissue within the lungs in the absence of any known cause. "Double-stranded RNA adenosine deaminase 1 (ADAR1) is significantly down-regulated in fibroblasts derived from Idiopathic Pulmonary Fibrosis (IPF) patients, and its overexpression restored levels of miRNA-21, PELI1, and SPRY2." (PMID 36012303, 2022).
Insulin resistance (1 paper, 2019). Increased resistance towards insulin, that is, diminished effectiveness of insulin in reducing blood glucose levels. "In the present study, we aimed to further understand SPRY2 via functional characterisation in HepG2 cells, an in vitro model of human hepatocytes widely used to investigate T2DM and insulin resistance." (PMID 31664995, 2019). "However, based on the GWAS findings, there is reason to believe that SPRY2 may also be involved in peripheral insulin resistance, metabolic syndrome or hepatosteatosis, rather than just insulin secretion." (PMID 31664995, 2019).
invasive ductal carcinomas (1 paper, 2011). "Spry2 gene expression was found to be lower in a panel of invasive ductal carcinomas compared to normal breast tissue, and lower in HER2-positive (by immunohistochemistry) tumours." (PMID 21909357, 2011).
Legius syndrome (1 paper, 2016). Legius syndrome, also known as NF1-like syndrome, is a rare, genetic skin pigmentation disorder characterized by multiple cafC)-au-lait macules with or without axillary or inguinal freckling. "SPRED1, recognized as the causative gene for Legius syndrome (OMIM #611431), interacts with SPRY2 that has been described as a causative OFC gene." (PMID 26561393, 2016).
leukemia (1 paper, 2015). A malignant (clonal) hematologic disorder, involving hematopoietic stem cells and characterized by the presence of primitive or atypical myeloid or lymphoid cells in the bone marrow and the blood. "miR-21 overexpression is closely associated with cancer cell proliferation, metastasis, and disease prognosis of MM, non-Hodgkin’s lymphoma, leukemia and various other non-hematological solid tumors miR-21 may regulate the expression of SPRY2." (PMID 25633921, 2015).
lung tumor (1 paper, 2018). "Furthermore, expression levels of the downstream markers of the corresponding microRNAs, namely PTEN, MARCKs, TPM-1, PDCD4, SPRY-2, ETS-1, ZEB-2, FGFRL-1, EFNA-3, and k-RAS were downregulated in the lung tumor lesions of patients with the underlying condition compared to non-COPD patients." (PMID 29371906, 2018).
malaria (1 paper, 2022). Malaria is a serious and sometimes fatal disease caused by a parasite that commonly infects a certain type of mosquito which feeds on humans. "We therefore, suggest further investigation of the disease immune mechanism associated with the SPRY2 and ITGB1BP1 PSGs towards Malaria." (PMID 35428239, 2022).
metastatic prostate carcinoma (1 paper, 2020). A carcinoma that arises from the prostate gland and has spread to other anatomic sites. "Genomic alterations of SPRY2 and PTEN as part of the RAS/ERK and PI3K/AKT pathways, respectively, have been detected in ∼40% of metastatic prostate cancer patients (SU2C/PCF Dream Team)." (PMID 33033111, 2020).
metastatic tumours (1 paper, 2020). "Other mutations included KDM5C (1/6, OVA_013), FLNA (1/6, OVA_378), RGS7 (1/6, OVA_047) and SPRY2 (1/6, OVA_365), which were also clonal in both primary and metastatic tumours." (PMID 32099096, 2020).
monoclonal gammopathy of undetermined significance (1 paper, 2015). "A total of 30 patients with MM, 15 with monoclonal gammopathy of undetermined significance (MGUS) and 20 normal control (NC) outpatients were selected for the detection of miR-21 and SPRY2 expression using reverse transcription-quantitative polymerase chain reaction." (PMID 25633921, 2015).
osteonecrosis (1 paper, 2021). A none disease characterized by death of bone tissue due to a lack of blood supply. "By contrast, bone marrow mesenchymal stem cell-derived exosomes carrying miR-122-5p promote osteoblast proliferation in osteonecrosis of the femoral head, regulating Sprouty RTK Signaling Antagonist 2 (SPRY2) via the RTK/Ras/mitogen-activated protein kinase (MAPK) signaling pathway." (PMID 34574045, 2021).
ovarian adenocarcinoma (1 paper, 2021). An adenocarcinoma that arises from the ovary. "It has been previously reported that SPRY2 overexpression inhibited the induction of the transcriptional repressor E-cadherin in the SKOV3 ovarian adenocarcinoma cell line." (PMID 34040530, 2021).
ovarian hyperstimulation syndrome (1 paper, 2016). A complication of ovulation induction in infertility treatment. "Moreover, we found that the expression levels of SPRY2 were significantly higher in the granulosa cells of ovarian follicles from IVF patients who later developed ovarian hyperstimulation syndrome (OHSS)." (PMID 27539669, 2016). "Interestingly, we showed that SPRY2 expression levels were significantly increased in granulosa cells of ovarian hyperstimulation syndrome (OHSS) patients." (PMID 27539669, 2016).
periodontal disease (1 paper, 2016). "Collectively, our results suggested that topical administration of Spry2 inhibitors may efficiently resolve inflammation in periodontal disease as macrophage‐based anti‐inflammatory immunotherapy and may create a suitable environment for periodontal wound healing." (PMID 27042307, 2016).
peripheral nerve injury (1 paper, 2011). Injury to a peripheral nerve. "Increased miR-21 levels enhanced neurite outgrowth from DRG neurons by targeting the SPRY2 protein, suggesting that axotomy-induced miR-21 plays a role in promoting axonal regeneration following peripheral nerve injury." (PMID 21853131, 2011).
peripheral nerve lesion (1 paper, 2019). "MiR-21 is upregulated in response to a peripheral nerve lesion and downregulates Spry2, but not PTEN, in DRG neurons." (PMID 32038175, 2019).
pituitary adenomas (1 paper, 2023). "The expression levels of ANXA2, PMAIP1, SPRY2, C2CD4A, APOD, FGF14 and FKBP10 were significantly upregulated while FNDC5 and MAP3K4 were downregulated in the invasive gonadotrophic pituitary adenomas compared to the non-invasive ones." (PMID 36750863, 2023).
rectal cancer (1 paper, 2021). A primary or metastatic malignant neoplasm that affects the rectum. "In this regard, SPRY2’s role in advanced rectal cancer may align with our previous reports that suggested a mechanistic function of SPRY2 as an oncogene and a positive regulator of EMT in CRC." (PMID 34685612, 2021). "A recent study identified a differential mRNA expression panel consisting of nine genes, in which SPRY2 was upregulated in patients with advanced rectal cancer who did not respond to preoperative chemoradiotherapy (PCRT)." (PMID 34685612, 2021).
renal agenesis (1 paper, 2022). Renal agenesis (RA) is a form of renal tract malformation characterized by the complete absence of development of one or both kidneys (unilateral RA or bilateral RA respectively), accompanied by absent ureter(s). "We then generated Spry1+/–; Spry2+/– mice either expressing Ret (RetEGFP/+) or not (RetEGFP/EGFP) and analyzed their caudal WDs by EGFP fluorescence at birth, since Ret-knockout animals die shortly after birth owing to renal agenesis." (PMID 36098804, 2022).
viral infection (1 paper, 2026). "Furthermore, we demonstrate that Spry2-deficient DCs retain an unaltered ability to stimulate CD8+ T-cell activation and proliferation, ultimately resulting in normal CD8+ T-cell effector differentiation during acute viral infection." (PMID 41929490, 2026).